DOCK4 (dedicator of cytokinesis 4)
Diseases named in the same sentence as DOCK4 in open-access papers (continued):
Sharing a sentence is not in itself a finding about the gene and the disease.
prostate carcinoma (2 papers, 2021 to 2024). A carcinoma that arises from epithelial cells of the prostate gland. "Dock4 mutations or depletion have been observed in ovarian and prostate cancers and were shown to contribute to tumorigenesis." (PMID 38802496, 2024). "Among them, the expression level of DOCK4 was the most different between normal and prostate cancer tissues." (PMID 34804930, 2021). "Overexpression of DOCK4 abolished the inhibition of miR-33b-3p on migration and invasion in prostate cancer cells." (PMID 34804930, 2021). "In summary, our findings demonstrate that miR-33b-3p suppresses metastasis by targeting DOCK4 in prostate cancer." (PMID 34804930, 2021). "The current study demonstrates that miR-33b-3p inhibits metastasis by targeting DOCK4 in prostate cancer." (PMID 34804930, 2021). "In this study, overexpression of wild type of DOCK4 promoted the migration and invasion of prostate cancer cells, supporting its function to mediate metastasis in prostate cancer." (PMID 34804930, 2021). "Whether miR-33b-3p exerted the motility-suppressing roles by targeting DOCK4 in prostate cancer was determined." (PMID 34804930, 2021).
Stroke (2 papers, 2023 to 2024). Sudden impairment of blood flow to a part of the brain due to occlusion or rupture of an artery to the brain. "Moreover, the predominant Mg0 subgroup at subacute stages (7d) after stroke expressed greater Nav3 and Dock4, pivotal for axon outgrowth, guidance, and cellular protection against oxidative stress, implying a neuroprotective potential." (PMID 38988493, 2024). "Because bioinformatics research revealed that DOCK4 might be a direct target of miR-181d, DOCK4 expression alterations in stroke models were also examined." (PMID 36882763, 2023).
adenoma (1 paper, 2025). A neoplasm arising from the epithelium. "Collectively, these findings validate the distinct expression patterns of TMOD2 and DOCK4 in colorectal carcinogenesis (from normal tissues to adenoma to cancer), and provide a molecular framework for understanding the role of the two genes in the pathogenesis of intestinal adenomas and carcinomas." (PMID 41378121, 2025).
cyst (1 paper, 2024). A sac-like closed membranous structure that may be empty or contain fluid or amorphous material. "Impaired adherens junction formation in HIF2α- or Dock4-deficient cells led to aberrant cyst morphogenesis in 3D kidney epithelial cell cultures." (PMID 38802496, 2024). "Thus, depletion of Dock4 led to similar morphological defects in MDCK cyst formation as was observed for HIF2α-KO cells." (PMID 38802496, 2024).
diabetic kidney disease (1 paper, 2021). Progressive kidney disorder caused by vascular damage to the glomerular capillaries, in patients with diabetes mellitus. "Taken together, our have found that USP36-mediated deubiquitination of DOCK4 contributes to the diabetic kidney disease via the Wnt/β-catenin signaling pathway." (PMID 33968925, 2021). "In brief, USP36-mediated deubiquitination of DOCK4 could contribute to the EMT in diabetic kidney disease via the Wnt/β-catenin signaling pathway." (PMID 33968925, 2021).
gastric cancer (1 paper, 2022). A primary or metastatic malignant neoplasm involving the stomach. "The qRT-PCR results showed that DOCK4 expression level of 28 HP-related prognostic genes was higher in gastric cancer tissues than in adjacent tissues." (PMID 36248367, 2022).
glioma (1 paper, 2010). A benign or malignant brain and spinal cord tumor that arises from glial cells (astrocytes, oligodendrocytes, ependymal cells). "Therefore, we speculate that DOCK4 influences the invasive potential of gliomas and that the DOCK4 alleles may differentially modulate this potential." (PMID 20824129, 2010).
hepatocellular carcinoma (1 paper, 2022). A malignant tumor that arises from hepatocytes. "Similarly, EBLN3P influenced the progression of hepatocellular carcinoma (HCC) by regulating the expression of DOCK4 via miR-144-3p." (PMID 35473552, 2022).
Hypertension (1 paper, 2021). The presence of chronic increased pressure in the systemic arterial system. "The human genetics data observed here is consistent with the simple hypothesis that reduced efficacy of DOCK4 in vivo could treat both hypertension and AD." (PMID 33541420, 2021).
invasive breast carcinoma (1 paper, 2020). A carcinoma that infiltrates the breast parenchyma. "High expression of DOCK4 is closely related to invasive breast cancer and subsequent bone metastasis, making it a potentially useful biomarker to predict the risk of tumor bone metastasis." (PMID 32457792, 2020).
ischemic stroke (1 paper, 2023). A stroke disorder caused by obstruction of blood flow to the brain, due to thrombotic (local blood clot formation) or embolic (due to a blood clot or other material traveling from another site) event. "Furthermore, the DOCK4 rs2074130 mutation was related to lower DOCK4 levels in ischemic stroke (IS) peripheral blood and higher susceptibility to IS." (PMID 36882763, 2023).
leukemia (1 paper, 2007). A malignant (clonal) hematologic disorder, involving hematopoietic stem cells and characterized by the presence of primitive or atypical myeloid or lymphoid cells in the bone marrow and the blood. "Thus far, differential expression of DOCK4 and SPARCL1 had never been associated to CD133+/CD34+ cell expansion or leukemias." (PMID 17559657, 2007).
metastatic prostate carcinoma (1 paper, 2023). A carcinoma that arises from the prostate gland and has spread to other anatomic sites. "ChIP-seq experiments have shown that AR targets DOCK4, and previous research has demonstrated that DOCK4 is overexpressed in PCa, leading to metastatic prostate cancer." (PMID 37686146, 2023).
microcephaly (1 paper, 2024). A congenital or acquired developmental disorder in which the circumference of the head is smaller than normal for the person's age and sex. "Our results, including clinical, molecular and functional data, suggest that loss-of-function variants in DOCK4 probable cause a variable spectrum of a novel neurodevelopmental disorder with microcephaly." (PMID 38526744, 2024).
prostate tumors (1 paper, 2021). "Furthermore, overexpression of DOCK4 was observed in primary prostate tumors compared with normal tissues in TCGA dataset." (PMID 34804930, 2021).
renal fibrosis (1 paper, 2021). A final common manifestation of a wide variety of chronic kidney diseases characterized by glomerulosclerosis and tubulointerstitial fibrosis. "Among these proteins, particularly interest is DOCK4, due to its function in activating Wnt/β-catenin signaling pathway, which is associated with renal fibrosis." (PMID 33968925, 2021).
squamous cell lung carcinoma (1 paper, 2013). A carcinoma arising from squamous bronchial epithelial cells. "Similarly, a biomarker singleton set of one gene, the DOCK4, provides 100% accuracy for differentiating between squamous cell lung carcinomas and normal lung." (PMID 23369236, 2013).
tumor (28 papers, 2007 to 2026). "Both global genetic deletion of a single Dock4 allele in tumour-bearing mice and targeted knockdown in the vasculature of xenograft tumours perturbed blood vessel lumen formation, supporting the findings in the tissue culture angiogenesis model." (PMID 26129894, 2015). "Down-regulated genes in E2-treated CD133+/CD34+ cells also included the newly characterized tumor suppressor genes DOCK4, a member of the CDM gene family, and SPARCL1, which encodes an extracellular matrix-associated glycoprotein." (PMID 17559657, 2007). "Mutations or reduced expression of DOCK4 is related to malignancies in breast, lung, brain and blood tissues as well as tumor metastasis." (PMID 33968925, 2021). "No corresponding association was found in patients who received zoledronate (HR 0.812, 95%CI 0.176–3.76, p = 0.790), suggesting that treatment with zoledronate may counteract the higher risk for bone relapse from high DOCK4‐expressing tumours." (PMID 30426503, 2019). "Differential expression analysis and ceRNA network analysis showed several tumor-associated transcripts (Dock4, Fmr1, Zfhx3, Ralb, Mll, Aoc3, and circHRH4) may involve in ALV-J-induced tumorigenesis." (PMID 30286182, 2018). "DOCK4 shows high discriminatory power between tumor and normal samples, with an area under the receiver operating characteristic (ROC) curve (AUC) of 0.819." (PMID 41821478, 2026). "On the other hand, another key splicing event, DOCK4, is highly expressed in immune cells within the tumor microenvironment." (PMID 40308585, 2025). "The regulation of VEGF-mediated angiogenesis and immune evasion mechanisms further highlights DOCK4's comprehensive involvement in creating a tumor-permissive microenvironment." (PMID 41378121, 2025). "Together with our findings, this highlights the dual role of DOCK4 in both tumor-intrinsic and immune-regulatory processes." (PMID 40529490, 2025). "This study identifies OIP5-AS1 as a tumor suppressor in LUAD that regulates the miR-429/DOCK4 regulatory axis, thereby inhibiting tumor cell proliferation, migration, and altering macrophage polarization within the TME." (PMID 40529490, 2025). "In summary, this study identifies OIP5-AS1 as a key regulator of LUAD progression through the miR-429/DOCK4 regulatory axis, affecting both tumor-intrinsic pathways and macrophage-mediated immune modulation." (PMID 40529490, 2025). "We explored the OV prognosis relevance of tumor immune subsets, with multiple covariates including age, ethnicity, DOCK4 expression, and tumor stages in a multivariable Cox proportional hazard model." (PMID 33613670, 2021). "c‐MAF expression is induced by TGFβ and a recent patent application showed that DOCK4 expression correlates with MAF expression within primary tumours." (PMID 30426503, 2019). "The data show that DOCK4 is required for generation of blood vessel lumens in tumours and that changes in blood vessel calibre by knockdown of DOCK4 impact on tumour hypoxia." (PMID 26129894, 2015). "DOCK4 expression was abundant in tumour blood vessels in vivo; therefore, we investigated if DOCK4 controls lumen formation in tumours." (PMID 26129894, 2015). "Delivery of two different DOCK4 shRNAs using this approach resulted in changes in the morphology of tumour blood vessels consistent with performance of the co-injected retroviral producer lines." (PMID 26129894, 2015). "In control tumours, ∼38% of vessels with lumens had larger calibre (>35 μm), compared with 21% in tumours grown in heterozygous Dock4 null mice, corroborating findings in the xenograft model." (PMID 26129894, 2015). "Homozygous deletion of Dock4 leads to early embryonic lethality; therefore, we employed Dock4 heterozygous mice in tumour experiments." (PMID 26129894, 2015). "Analysis of all identifiable lumenized vessels in tumour sections showed decrease in lumen size in tumours grown in Dock4 heterozygous mice compared with controls." (PMID 26129894, 2015).
tumor (continued). "Similar to other DOCK family members such as DOCK2—which exhibits either tumor-suppressive or tumor-promoting roles depending on the specific tumor context and immune microenvironment—DOCK4 is involved in diverse signaling pathways in LUAD, including MYC signaling and DNA repair." (PMID 40529490, 2025). "It specifically examined whether OIP5-AS1 regulates macrophage polarization and tumor progression by acting as a competing endogenous RNA (ceRNA) that interacts with miR-429 to modulate DOCK4 expression." (PMID 40529490, 2025). "Targeting DOCK4 could be a potential strategy to regulate anti-tumor metabolism and immunity simultaneously." (PMID 40308585, 2025). "Given that Rac1 also plays a key role in the migration of immune cells such as macrophages, it is plausible that DOCK4 may influence macrophage trafficking within the tumor microenvironment." (PMID 40529490, 2025). "This complexity suggests that DOCK4 may act as an integrative node influenced by external cues and tumor microenvironmental factors, contributing to the dynamic regulation of both tumor progression and immune modulation." (PMID 40529490, 2025). "Through Rac activation, DOCK4 promotes aberrant cell proliferation by accelerating G1/S phase transition, facilitates tumor cell migration and invasion via cytoskeletal remodeling, and potentially mediates epithelial-mesenchymal transition through transcriptional reprograming." (PMID 41378121, 2025). "Notably, DOCK4 emerges as a suppressor of tumor growth by modulating tumor cell adhesion and invasiveness." (PMID 39026674, 2024). "Besides the ability to activating Rac1, Dock4 is also known to have Rap1 GEF activity in tumor cells." (PMID 32009906, 2019). "Previous studies have linked DOCK4 to immune cell infiltration in tumors, suggesting that its alternative splicing events in DMG may serve as a bridge between tumor metabolism and tumor immunity." (PMID 40308585, 2025). "Therefore, further investigations are required to determine whether DOCK4 influences macrophage polarization through the modulation of tumor-derived cytokines and chemokines." (PMID 40529490, 2025). "The results showed that GPX3 and DOCK4 expression was significantly upregulated in normal cell lines, while LDHA expression was significantly upregulated in tumor cell lines." (PMID 38213730, 2024). "In line with this, using xenograft mouse models, we show that DOCK4 plays a key role in promoting the extravasation of cancer cells through the brain capillaries in vivo, while it does not affect tumour growth and progression in the brain." (PMID 38762624, 2024). "In addition to analyzing the tumor-suppressive effects of ABR, PREX1, DOCK2, and DOCK4 through bioinformatics, we further verified the role of ABR in proliferation, migration, and cloning ability in PC9 and H1703 cells experimentally." (PMID 34783629, 2021). "Tumours DOCK4 shRNAs targeted to the vasculature lacked large calibre lumens compared with controls." (PMID 26129894, 2015). "Control tumours had CA-IX-positive hypoxic regions around the necrotic centre; necrotic regions were less prominent with DOCK4 shRNA, although hypoxia was observed in areas lacking larger lumens." (PMID 26129894, 2015). "Although we cannot exclude contribution of non-vascular cell types in the observed effects of DOCK4 genetic deletion in blood vessel development, altogether the data show that DOCK4 regulates blood vessel lumens in tumours and during development in vivo." (PMID 26129894, 2015). "Although DOCK4 is not a candidate marker for predicting the disease progression in LUSC patients, its higher expression is markedly correlated with delayed tumor progression in LUAD patients." (PMID 34783629, 2021).
cancer (15 papers, 2007 to 2025). A tumor composed of atypical neoplastic, often pleomorphic cells that invade other tissues. "It is increasingly recognized that DOCK4 induced Rac activation and Wnt/β-catenin pathway to stimulate cell polarization, migration, and invasion, which are associated with cancer progression and metastasis." (PMID 33613670, 2021). "Since DOCK4 as a member of the DOCK family is targeted by PPARs which shows close association with numerous cancer types, we characterized the expression of DOCK4 in 24 cancers." (PMID 33613670, 2021). "Previous studies have shown an association of DOCK4 and the metastatic phenotype of cancer cells." (PMID 38762624, 2024). "DOCK4 is crucial for cancer cell extravasation to the brain, with EGFR activation driving cell elongation reversed by Afatinib." (PMID 38762624, 2024). "The correlation coefficient between HIF2A and DOCK4 expression in different types of cancers according to GEPIA was up to 0.7 (p = 0), which demonstrates a significant correlation." (PMID 38802496, 2024). "The results of qRT-PCR indicated that the mRNA level of DOCK4 was higher in carcinoma tissues than those in normal tissues (P = 0.0126)." (PMID 36248367, 2022). "Such examples include DOCK-controlled motility resulting in metastasis in cancer (DOCK1), deficient axon organization potentially resulting in a neurological disorder (DOCK4), or deficient immune cell migration resulting in immunodeficiency (DOCK8)." (PMID 33684443, 2021). "In parallel with the importance of immune response in cancers, our results further confirmed that DOCK4 was mainly enriched in neutrophils." (PMID 33613670, 2021). "Further survival analysis demonstrated that DOCK4 indeed correlates with prognosis of some cancer types." (PMID 33613670, 2021). "To evaluate the possibility of DOCK4 as a prognostic marker in different tumors, we applied different cancer tissue RNA-Seq datasets from TCGA datasets." (PMID 33613670, 2021). "The result shows that DOCK4 is upexpressed in 9 cancer species and downexpressed in 15 cancer species which may be due to the distribution and function of DOCK family 11 members which are variant in different tissues and cells." (PMID 33613670, 2021). "As a first step, we chose to study DOCK4 and DOCK9 among a large family of GEFs, given that DOCK4 and DOCK9 have been demonstrated to respectively activate Rac1 and Cdc42 and that mutations in DOCK4 and DOCK9/Zizimin1 have been found in a number of cancers." (PMID 32143485, 2020). "Hence, the downregulation of ABR, PREX1, DOCK2, and DOCK4 promotes cancer development and leads to a poor prognosis by activating MYC and DNA repair signaling pathways in NSCLC, and further in vitro and in vivo studies are necessary to further confirm their association." (PMID 34783629, 2021). "Our study suggests that EGFR and DOCK4-mediated RAC1 activation in response to secreted brain endothelial factors oppose this contractile phenotype, allowing cancer cells to cross the endothelium and propel themselves into the brain parenchyma." (PMID 38762624, 2024). "Our results showed that control and DOCK4-depleted cancer cells almost double their filopodia in response to EGF treatment, whereas upon TGFβ stimulation, the number of filopodia remained unchanged in both control and DOCK4-depleted cells." (PMID 38762624, 2024). "Blocking the elongated morphology but not filopodial protrusions by knockdown of the RAC GEF DOCK4 inhibits cancer cell intercalation in vitro, and brain extravasation in vivo." (PMID 38762624, 2024). "Knockdown of DOCK4 and DOCK9 was also reported to reduce cancer growth." (PMID 32143485, 2020). "In addition, NSCLC subgroups with higher nodal metastasis levels or cancer stages generally have lower median expression of ABR, PREX1, DOCK2, and DOCK4, whereas statistical significance for the comparison among these subgroups remains to be verified with a larger number of samples." (PMID 34783629, 2021).
neurodevelopmental disorder (2 papers, 2024 to 2025). A behavioral and cognitive disorder with onset during the developmental period that involves impaired or aberrant development of intellectual, motor, or social functions.
infection (1 paper, 2025). The state of being infected such as from the introduction of a foreign agent such as serum, vaccine, antigenic substance or organism. "Top downregulated DEGs in bystander cells indicated a decreased enrichment of certain pro-inflammatory cytokines and signaling molecules in ADE compared to conventional infection conditions, including CXCL11, CXCL10, CCL2, DOCK4, STAT1, and JAK2." (PMID 39902963, 2025).